CASR (calcium sensing receptor)
Diseases named in the same sentence as CASR in open-access papers (continued):
Sharing a sentence is not in itself a finding about the gene and the disease.
hypoparathyroidism (continued). "In addition to a potential treatment for ADH1, calcilytics could also have a role in reducing urinary excretion of calcium in other patients with hypoparathyroidism, through blocking the renal CASR." (PMID 27803672, 2016). "Therefore, the hypoparathyroidism and short stature described in this case are unlikely to be related to the CaSR Leu616Val variant and may be due to mutations in other genes." (PMID 39658204, 2025). "For instance, in APS-1 with hypoparathyroidism, NLR family pyrin domain containing 5 (NLRP5) and calcium-sensing receptor (CaSR) have been identified as parathyroid autoantigens." (PMID 30002654, 2018). "The measurement of anti-CaSR antibodies seemed not very sensitive for the diagnosis of hypoparathyroidism in our study, as these autoantibodies were present in only 2/19 patients with hypoparathyroidism." (PMID 38605470, 2025). "Candidate autoantigens previously linked to the development of hypoparathyroidism in APECED patients, as the calcium sensing receptor (Ca-S-R) has not been confirmed as relevant autoantigen." (PMID 23133448, 2012). "Since we could not detect significant titers of anti-CaSR antibodies in our patient, it seems the pathomechanism is probably distinct from the one seen in sporadic hypoparathyroidism." (PMID 30791949, 2019). "In addition, autoantibodies against the calcium-sensing receptor (CaSR) were detected in almost 40% of Finnish APECED patients, although this study questioned the specificity and sensitivity of anti-NLRP5 and CaSR antibodies as markers of hypoparathyroidism." (PMID 31548517, 2017). "Assessment of anti-calcium sensing receptor (CaSR) antibodies and genetic testing for Glial Cell Missing-2 (GCM2) would also be appropriate to do to rule out autoimmune disease, due to its high prevalence in hypoparathyroidism." (PMID 35036185, 2021).
kidney stones (51 papers, 2011 to 2026). "Genetic predisposition, such as variations in the calcium-sensing receptor (CasR), has been linked to altered calcium metabolism, further predisposing individuals, particularly those of African descent, to kidney stones." (PMID 41149617, 2025). "A previous genome-wide association study (GWAS) reported several novel loci for nephrolithiasis in British and Japanese population, some of which were predicted to influence CaSR signaling." (PMID 35910217, 2022). "In summary, sequencing of the CaSR locus in Pakistani stone formers reveals a novel loss-of-function variant atypically associated with nephrolithiasis." (PMID 34772415, 2021). "Sequencing of the CaSR locus in Pakistani stone formers reveals a novel loss-of-function variant, expanding the connection between the CaSR locus and nephrolithiasis." (PMID 34772415, 2021). "Aberrant Ca2+ sensing by the kidney and VSMCs, owing to altered CaSR expression or function, is associated with the formation of nephrolithiasis and vascular calcification." (PMID 33808324, 2021). "Several polymorphisms of the CALCR and CASR genes were also associated with recurrent kidney stones." (PMID 33956883, 2021). "Overall, the novel variant expands the connection between rare inactivating CaSR variants and nephrolithiasis." (PMID 34772415, 2021). "Of note, in patients with primary hyperparathyroidism, relative hyperoxaluria, hypomagnesuria as well as polymorphic variants of the gene encoding the calcium sensing receptor have been identified as factors significantly associated with kidney stones." (PMID 34977081, 2021). "Some other calcium transport proteins including calcium-sensing receptor (CaSR) have been reported to be associated with hypercalciuria and nephrolithiasis." (PMID 30737304, 2019). "Our previous study also showed a significant association between CASR (rs17251221) and stone multiplicity in nephrolithiasis patients." (PMID 31754202, 2019). "Our study further indicated that rs7627468 in CASR was associated with pH values and the calcium/creatinine ratio in urine of nephrolithiasis patients." (PMID 31754202, 2019). "HD patients having nephrolithiasis as a cause of ESRD differed in the CASR rs7652589 SNP compared with other HD patients." (PMID 27739473, 2016). "In different populations, a polymorphism in the CaSR gene leading to the Arg990Gly mutation has been reported to be associated with hypercalciuria and nephrolithiasis." (PMID 27965733, 2016). "The A allele of CASR rs7652589 was recognized in our study as a risk allele for severe nephrolithiasis, among other possible factors, such as gender, age, serum concentrations of Ca and PTH, and the G allele of CCL2 rs1024611." (PMID 27739473, 2016). "An association between the CASR rs7652589 SNP and nephrolithiasis remained significant after adjusting for gender and age at the onset of RRT." (PMID 27739473, 2016). "Gender, age, serum concentrations of Ca and PTH, the G allele of CCL2 -2518 A > G (rs1024611), and the A allele of CASR rs7652589 were entered into the multivariate stepwise linear regression model as possible determinants of nephrolithiasis-related ESRD." (PMID 27739473, 2016). "Among these factors, only the A allele of CASR rs7652589 was an independent determinant of nephrolithiasis-related ESRD (B 0.09, 95% CI 0.01–0.17, P = 0.020)." (PMID 27739473, 2016). "A comparison of idiopathic calcium stone formers and healthy controls revealed one SNP (rs6776158 [A>G]) located in the CASR P1 promoter that was associated with nephrolithiasis." (PMID 27679579, 2016). "It should be noted that CCL2 rs1024611 and IL18 rs360719 yielded borderline associations with nephrolithiasis-related ESRD simultaneously with a significant association with the CASR rs7652589 SNP." (PMID 27739473, 2016). "But single nucleotide polymorphisms (SNPs) within the regulatory regions of the CASR gene have also been associated with kidney stone risk, for example, in primary hyperparathyroidism." (PMID 27679579, 2016).
kidney stones (continued). "The A allele of CASR rs7652589 was also a significant determinant of nephrolithiasis-related ESRD among other possible determinants such as gender, age, serum concentrations of Ca and PTH, and the G allele of CCL2 rs1024611." (PMID 27739473, 2016). "A total of 58 variants, strongly correlated with rs7627468 (r2>0.95) and located within intron 1 of CASR, associate with kidney stones." (PMID 26272126, 2015). "After the three genome-wide significant loci for kidney stones, we observe a suggestive association of rs7627468[A] in the first intron of CASR at 3q21.1 encoding the calcium-sensing receptor (MAF=26.80%; OR=1.16, P=2.0 × 10−8)." (PMID 26272126, 2015). "The kidney stone variant rs7627468 and other linked variants associated with kidney stones are located within intron 1 of CASR that entails a regulatory region." (PMID 26272126, 2015). "The number of renal stones is related to the disease activity of nephrolithiasis; therefore, we investigated the association between the CASR genetic polymorphism and the number of renal stones in patients with nephrolithiasis." (PMID 21966463, 2011). "Few studies considering CaSR as a candidate-gene tested the frequency of their alleles in nephrolithiasis." (PMID 22107799, 2011). "Moreover, our functional studies of rare coding, KSD-associated DGKD variants are consistent with DGKδ-mediated impaired CaSR signal transduction in the pathophysiology of nephrolithiasis." (PMID 40372791, 2025). "Moreover, additional studies are required to define the cells and tissues via which impaired DGKδ-mediated CaSR signal transduction causes increased kidney stone risk." (PMID 40372791, 2025). "Furthermore, we demonstrate that cinacalcet, a positive CaSR allosteric modulator, ameliorated impaired CaSR-mediated signaling due to rare kidney stone–associated DGKδ missense mutations and normalized biased CaSR signal transduction in DGKδ-depleted cells." (PMID 40372791, 2025). "However, the underlying molecular mechanisms that link CaSR genetic variability to kidney stones are still uncovered." (PMID 36467702, 2022). "Finally, the CaSR has also been associated to nephrocalcinosis and nephrolithiasis, common inflammatory renal defects, which are also recurrent morbidities in ADH patients and are strongly associated with hypercalciuria." (PMID 36467702, 2022). "In addition, DGKH is associated with the formation of kidney stones by affecting calcium sensitive receptor (CasR) signaling and calcium metabolism in the body." (PMID 36482994, 2022). "The polymorphism of the CaSR gene Arg990Gly was related to hypercalciuria and nephrolithiasis." (PMID 33678127, 2021). "Overall, our study reveals a novel rare CaSR variant associated with nephrolithiasis and suggests that specific inactivating variants in CaSR may have distinct effects on its role in calcium homeostasis." (PMID 34772415, 2021). "For these reasons, the CaSR locus was sequenced in a cohort of 57 Pakistani families with pediatric NL, revealing rare loss-of-function variants in Pakistani kindreds with pediatric nephrolithiasis." (PMID 34772415, 2021). "However, several CaSR gene polymorphisms have been linked to kidney stones in human, suggesting that intact CaSR function in CD is critical to renal adaptations to enhanced luminal Ca2+ concentrations." (PMID 32659887, 2020). "Furthermore, Ala986Ser in exon 7 of CASR was repeatedly reported to be associated with a risk of kidney stones and serum calcium concentrations in different ancestries." (PMID 31754202, 2019). "We hypothesized that the nephrolithiasis-associated loci linked to CaSR-signaling associate with enhanced CaSR signal transduction resulting in a biochemical phenotype mimicking an attenuated form of ADH." (PMID 31729369, 2019). "Moreover, several studies reported associations of CASR variations with nephrolithiasis or other kidney-related clinical manifestations." (PMID 31754202, 2019).
kidney stones (continued). "CaSR, the encoding gene of which is a candidate gene for nephrolithiasis, may underlie the predisposition of some individuals to calcium nephrolithiasis." (PMID 27965733, 2016). "The aim of the study was to determine the associations of the CASR rs7652589 SNP with nephrolithiasis-related ESRD, Ca, P, alkaline phosphatase (ALP), PTH, response to treatment with cinacalcet, prevalence of CAD, including MI, as well as all-cause and cardiovascular mortality in HD patients." (PMID 27739473, 2016). "Variations in intron 1 might specifically influence gene expression in the kidney influencing the ability of CASR to respond to extracellular calcium and in this way increase the risk of kidney stone formation." (PMID 26272126, 2015). "frequencies for CASR rs17251221 and nephrolithiasis susceptibility." (PMID 21966463, 2011). "However, the genetic effect of CASR (rs17251221) on susceptibility to nephrolithiasis is still unclear." (PMID 21966463, 2011). "The fact that activation of the CaSR in the renal tubules triggers calciuria with subsequently elevated risk of nephrolithiasis can be neglected in a state of renal insufficiency such as secondary HPT but not in primary HPT or persisting HPT after kidney transplantation." (PMID 21461394, 2011). "We further evaluated whether an association existed between CASR and the characteristics of kidney stone patients, including age, gender, number of stones, and frequency and family history of stones." (PMID 21966463, 2011). "Association analysis between CASR rs17251221 and subgroups of 189 patients with kidney stone." (PMID 21966463, 2011). "Our studies, which have not examined the physiological effects of DGKδ dysfunction, indicate that additional investigations are required to define the cells and tissues via which impaired DGKδ-mediated signal transduction via the CaSR and other GPCRs may cause increased kidney stone risk." (PMID 40372791, 2025). "Gene polymorphisms that reduce CaSR expression may impair the protective effect of CaSR on calcium phosphate and oxalate precipitation, making it more likely to cause kidney stones, while activating the polymorphism rs1042636 may predispose to calcium stones by increasing calcium excretion." (PMID 41208959, 2025). "In 2019, a research team found that among patients with nephrolithiasis, individuals with the GG allele at the rs7627468 variant of the calcium-sensing receptor (CASR) gene have lower pH levels in urine, which may explain the involvement of CASR in stone formation." (PMID 39588149, 2024). "Finally, a dysfunction in CaSR may be the possible mechanism underlying vascular calcification and nephrolithiasis." (PMID 33808324, 2021). "This study reveals the potential role of the novel CaSR-PKA-FOXO4-SLC26A6 signaling pathway in the pathogenesis of kidney stones." (PMID 41938536, 2026). "To summarize, targeted inhibition of PKA and STAT3 can attenuate the stimulatory impact of CaSR on claudin-14, thus inhibiting kidney stone formation." (PMID 39697555, 2024). "Our previous study demonstrated that CaSR and claudin-14 expression was enhanced during the modeling of kidney stones in rats." (PMID 39697555, 2024). "The calcium-sensitive receptor (CaSR) has been identified as a key factor in the formation of kidney stones." (PMID 39697555, 2024). "Eventually, a Cldn-14 knockout rat model and a model of kidney stone induction by ethylene glycol were generated using CRISPR-Cas9 technology to further clarify the role of claudin-14 in the CaSR-regulated formation of kidney stones." (PMID 39697555, 2024). "To further elucidate the role of PKA and STAT3 in the CaSR-claudin-14 pathway, we treated a rat model of ethylene glycol-induced kidney stones by co-administering the CaSR activator R568 along with the PKA inhibitor or the STAT3 inhibitor." (PMID 39697555, 2024).
kidney stones (continued). "In this study, for the first time we aimed to determine the promoter methylation status of VitD R, Claudin, and CaSR in recurrent kidney stone formation." (PMID 35546405, 2022). "A recent meta-analysis identified 20 nephrolithiasis-associated loci, including CYP24A1, DGKD, DGKH, WDR72, GPIC1, and BCR locus which were predicted to affect vitamin D metabolism and calcium-sensing receptor signaling respectively." (PMID 35439979, 2022). "Owing to the critical role of CaSR in controlling physiological and pathological calcifications, we also addressed the impact of Ca signaling on vascular calcification and nephrolithiasis." (PMID 33808324, 2021). "In the present study, we used gadolinium chloride (GdCl3, agonist of CaSR) and NPS 2390 (antagonists of CaSR) to explore the effects of CaSR on nephrolithiasis in rats." (PMID 33678127, 2021). "Among nephrolithiasis patients, subjects with GG at rs7627468 (calcium-sensing receptor (CASR)) have lower pH level in urine (p = 0.0088)." (PMID 31754202, 2019). "Our findings indicate that studies of genotype-guided precision-medicine approaches, including withholding vitamin D supplementation and targeting vitamin D activation or CaSR-signaling pathways in patients with recurrent kidney stones, are warranted." (PMID 31729369, 2019). "Prevalence of nephrolithiasis-related ESRD significantly differed in patients stratified by CASR rs7652589 genotype." (PMID 27739473, 2016). "In this study, we have shown that an epistatic interaction between the CASR rs7652589 SNP (risk allele A) and CCL2 rs1024611 (risk allele G) is associated with nephrolithiasis-related ESRD requiring regular dialysis treatment." (PMID 27739473, 2016). "We investigated polymorphisms in 200 kidney stone patients and 200 controls by direct sequencing of VDR, CaSR and CLDN14 genes." (PMID 26107257, 2015). "In summary, we observe two uncorrelated signals (r2=0.0073) at the CASR locus, one for serum calcium only (rs73186030) and one mainly for kidney stones (rs7627468)." (PMID 26272126, 2015). "We identify sequence variants associating with kidney stones at ALPL (rs1256328[T], odds ratio (OR)=1.21, P=5.8 × 10−10) and a suggestive association at CASR (rs7627468[A], OR=1.16, P=2.0 × 10−8)." (PMID 26272126, 2015). "In conclusion, this study defines 3 common putative KSD-causing variants and demonstrates the central role of the DGKδ-mediated reduction of CaSR signal transduction, increased renal phosphate excretion, and perturbed 1,25 vitamin D inactivation in kidney stone pathogenesis." (PMID 40372791, 2025). "Therefore, this study aimed to elucidate the relationship between the CaSR-claudin-14 pathway and stone formation, and to clarify how CaSR modulates claudin-14 expression, exploring potential intervention points for kidney stones." (PMID 39697555, 2024). "At the molecular level, the dysfunction of the calcium-sensing receptor (CaSR) might be the missing link between nephrolithiasis and CVD." (PMID 36766999, 2023). "SNPs of DGKH was predicted to promote kidney stone formation by influencing CaSR signaling." (PMID 35910217, 2022). "Genetic studies have revealed that the following have important roles in the etiology of kidney stones: transporters and channels; the calcium-sensing receptor signaling pathway; the metabolic pathways for vitamin D; oxalate, cysteine, amino acids; purines and uric acid)." (PMID 35612621, 2022). "A published study suggested that CaSR was part of a common pathway in nephrolithiasis formation." (PMID 33678127, 2021). "The results suggest that CaSR might play significant roles in the induction of nephrolithiasis in rats by regulating reactive oxygen species (ROS) and PS ectropion and the composition of urine, OPN, KIM-1, and ERK expression." (PMID 33678127, 2021).